EPCAM (epithelial cell adhesion molecule)
Diseases named in the same sentence as EPCAM in open-access papers (continued):
Sharing a sentence is not in itself a finding about the gene and the disease.
cancer (continued). "Homotypic targeting with polyvalent recognition: Cancer-cell membranes display a mosaic of adhesion molecules (EGFR, E-cadherin, EpCAM, integrin αvβ3, etc.)." (PMID 41155938, 2025). "Like many OVs, Ad5NULL-A20 can broaden its therapeutic potential through the design of BICA targeting alternative TAA such as EPCAM and HER2, for applications in cancers that lack EGFR or MICA." (PMID 40741595, 2025). "Our results showed that MBZ significantly down-regulated cancer stemness markers, including CD24, CD44, and EpCAM, in both OVCAR3 and OAW42 cells, but the effects were more pronounced in OVCAR3 cells." (PMID 39851541, 2025). "However, the role of EpCAM in cancer metastasis remains unclear." (PMID 39996844, 2025). "Taken together, EpCAM cleavage by ADAM17 and γ-secretase promotes cancer stem cell renewal via EpICD-mediated transcription." (PMID 39996844, 2025). "We successfully profiled EVs derived from human cancer cell lines and a plasma cancer patient using aptamers against the most typical exosomal CD63 and cancer EpCAM proteins." (PMID 41373484, 2025). "In the literature, markers such as cytokeratin, EpCAM, Ki67, and CD90 allow the confirmation of the presence of cancer cells." (PMID 39941799, 2025). "Both genes are connected with other genes notably deregulated in cancer as ANGPTL1, ADAMTSL2, PELI2 and EPCAM." (PMID 41231825, 2025). "Antibody-DNA conjugates were used to recognize the epithelial cell adhesion molecule (EpCAM) antigen on the TAE surface and quantify the antigen using qPCR for cancer analysis." (PMID 39911266, 2025). "This was further supported by the significant changes in cancer stem cell (CSC) marker expression (CD133, CD24, EPCAM) corresponding to MORF4L1 expression levels." (PMID 39757177, 2025). "EpCAM, HER2, CD44, and IGF1R were simultaneously detected and distinguished on four three different cancer cells lines (SK-BR-3, MDA-MB-231, and MCF-7)." (PMID 39997827, 2025). "A notable finding in this study was the cancer-type specificity observed among TACT markers, such as EPCAM and ERBB2, which displayed differential expression patterns between CRC and BC." (PMID 40003943, 2025). "The epithelial OC origin of the PDC2 and PDC3 samples was confirmed by the expression of OC-specific markers PAX8 and CD24, epithelial makers MKI67, EPCAM, KRT8 and KRT18 and cancer stem cell markers such as CD44 and ROR1." (PMID 39482470, 2025). "This study demonstrated that EpCAM-NIR-PIT, particularly when combined with immune-activating agents such as anti-PD-1, is a promising new approach for cancer treatment, inducing durable and systemic anticancer immunity." (PMID 40792441, 2025). "It is noteworthy that many known genes in cancer, e.g., HIF1A, SLC16A3, EPCAM, and SOX9, were consistent, albeit in fewer datasets and so did not meet our inclusion criteria." (PMID 39774001, 2025). "A dose-dependent in vitro anti-proliferative response to BsADCs was observed in the EpCAM and CLDN3 high-expressing OVCAR-3 and NCI-H1781 cancer cells." (PMID 40057807, 2025). "EpCAM and CD133 peptides allowed for receptor-mediated endocytosis, thereby increasing the L uptake and internalization by cancer stem cells." (PMID 40006612, 2025). "Thus, precise EpCAM signaling may present an accurate relationship between EpCAM and cancer cells." (PMID 39996844, 2025). "Previously, we reported on the peptide–HLA-I fusion protein EpCAM-ReTARGTPR, which allows us to redirect the cytotoxic activity of pre-existing anti-CMV CD8pos T cell immunity to selectively eliminate EpCAMpos cancer cells." (PMID 40243928, 2025). "The results showed that cancer cell marker genes, such as CDH1, EPCAM, FOXA1, and GATA3, were enriched within the spatial domain (sections (−120, −90], (−90, −60], (−60, −30] and (−30, 0])." (PMID 39965034, 2025).
cancer (continued). "EpCAM, also called TACSTD1, is a cell surface protein specifically expressed in epithelial tissues, and overexpressed in most human carcinomas." (PMID 39572744, 2025). "Further exploratory analyses revealed that CTLA4, PDCD1, and the cancer antigens MSLN, MUC1, EPCAM, and PROM1 presented significantly increase expression levels in the high-risk subtype group." (PMID 39712016, 2024). "Subsequently, the LUAD marker genes NAPSA, NKX2-1, the LUSC marker genes TP63, KRT5, as well as EPCAM and MET were adopted to identify the cancer cell clusters." (PMID 38382091, 2024). "Within the clinical practice and oncology research, several clinically established cancer stem cell markers exist, including CD24, CD44, CD133, ALDH1, and EpCAM." (PMID 39435289, 2024). "Expression of EpCAM and PTPRC (CD45) are shown as positive controls for cancer cells and immune cells, respectively." (PMID 39224600, 2024). "Membrane EpCAM is cleaved by ADAM17/TACE in the extracellular space; however, high expression of ADAM17/TACE is observed only in some cancer cells." (PMID 38791091, 2024). "Epithelial Cell Adhesion Molecule (EpCAM), also known as CD326, is known for its role in cell-cell adhesion in the epithelia, but its roles exceed this in cancer." (PMID 38965243, 2024). "Regardless, the abundance of evidence implicating EpCAM as a CSC marker and its role in promoting aggressive cancer implicate it as an attractive target for anti-cancer agents." (PMID 38612911, 2024). "qPCR analysis of EPCAM (epithelial cancer cell marker) and CD45 (pan-immune cell marker) confirmed the purity of the isolated cancer cells." (PMID 38992037, 2024). "A more recently developed anti-EpCAM immunotoxin, scFv2A9-PE, similarly uses the Pseudomonas aeruginosa exotoxin and exhibits an IC50 of 50 pM for cytotoxicity in EpCAM+ HHCC hematopoietic cells; however, it has yet to be tested against cancer cells." (PMID 38612911, 2024). "It was shown in a different study that EpCAM-CAR T cells have significant killing effects on PC3M prostate cancer cell line and significant inhibition of cancer growth in vivo." (PMID 39312080, 2024). "The variability in EpCAM expression is primarily regulated by the process of epithelial–mesenchymal transition (EMT), which is a key mechanism promoting cancer cell invasion, migration, and dissemination." (PMID 38675353, 2024). "EpCAM (CD326), a human cell surface glycoprotein that is 39–40 kDa in size and widely expressed in a variety of cancer cells, including ovarian, breast, colorectal, prostate, lung, and pancreatic, is one of the more alluring targets for immunotherapy." (PMID 38243252, 2024). "These included, but were not limited to: PECAM1 and CDH5 (EC markers), PDGFRA (fibroblast marker), PDGFRB (pericyte marker), and EPCAM and KRT18 (cancer cell markers)." (PMID 38183074, 2024). "This study aims to evaluate the preclinical potential of epithelial cell adhesion molecule (EpCAM)-binding DARPins as targeting moieties for near-infrared fluorescence (NIRF) and photoacoustic (PA) imaging of cancer." (PMID 37642704, 2024). "In other cancers, transcription factors, including LEF1, Sp1, NF-κB, STAT3, and ETS1, have been demonstrated to be indispensable for EpCAM expression." (PMID 38791091, 2024). "EpCAM has been established as a key CSC antigen in CRC and several other cancer types, and it can also be considered a pivotal contributor to Wnt signaling due to the association of EpICD with β-Catenin." (PMID 39010070, 2024). "LCSCs are characterized by specific surface markers, such as CD133, CD90, the epithelial cell adhesion molecule (EpCAM), CD24, and CD13, which distinguish them from the bulk of differentiated cancer cells." (PMID 39769068, 2024). "A microfluidic platform, consisting of microchannels functionalized with antibodies against either EpCAM or CD133 biomarkers, was similarly constructed to isolate CTCs and CCSCs from blood sample of cancer patients." (PMID 39459070, 2024).
cancer (continued). "They showed that completely reversed spheroids reproduce metastasis features in vivo, such as migration/invasion, chemoresistance and cancer stem cell marker expression (CD133, CD90, EpCAM)." (PMID 39056658, 2024). "This was achieved by targeting EpCAM, CD49b, and CD51, which play crucial roles in cell adhesion, migration, metastasis, and signaling — key processes in cancer progression 34-37." (PMID 39479442, 2024). "Intriguingly, we also found that the cancer stem cells (CSC) score, calculated using common CSC markers (EPCAM, CD24, KRT19, SOX9, PROM1, CD44, THY1, CD47), was significantly higher in the EMT-subtype." (PMID 39095854, 2024). "However, EPCAM is specific for well-differentiated epithelial cells and is one of the first epithelial markers lost on CTCs during the epithelial-to-mesenchymal transition (EMT) process before other epithelial markers which is associated with increased invasiveness and metastasis of cancer cells." (PMID 39441869, 2024). "Our data highlighted a significant enrichment of certain cellular adhesion molecules, including MCAM, EpCAM, ICAM-1, EGFR, and ALCAM, in cancer EVs relative to hTERT-immortalized MSC EVs." (PMID 38786083, 2024). "In contrast to previous studies that focused on ITGAV expression in mesenchymal EpCAM− cancer cells, our data show an increased ITGAV expression within epithelial EpCAM+ cancer cells that correlates with the emergence of epithelial plastic cancer cells." (PMID 39075581, 2024). "Clinical trials have shown that it is able to detect exosomes directly from 2 μL plasma samples, and indicated that cancer patients have higher levels of CD63, EpCAM double-positive exosomes than healthy controls." (PMID 39617822, 2024). "Network analysis of upregulated genes revealed their enrichment in signatures of cancer cell growth and fetal liver (e.g., AFP, DLK, EPCAM and KRT19)." (PMID 37173882, 2023). "Primary culture of the malignant tumors of the converted cells exhibited the elevated expression of CSC related genes CD44, CD24 and EPCAM maintaining the expression of stemness genes." (PMID 37181678, 2023). "Cancer cells with high glycolysis can release a large number of exosomes containing cancer stemness markers, including ABCG2, ALDH1A1, and EpCAM." (PMID 37919747, 2023). "By establishing the presence of the surface marker EpCAM, which the MCF‐7 cell line overexpressed, we further demonstrated that the growing MCTSs retain the cancer cell characteristics." (PMID 37402278, 2023). "An evolution of TriKE format is TetraKE, which has been described to simultaneously engage EpCAM and CD133 for targeting carcinoma cells and cancer stem cells, along with a CD16-engaging moiety and IL-15 for NK cell expansion." (PMID 36793863, 2023). "P0825 expressed high levels of cancer markers KRT19 and EpCam, cancer stem marker Sox9, Hippo oncogenic co-activator Yap1, and EMT marker Vimentin." (PMID 36865791, 2023). "Epithelial-derived cancer cells (CD45-negative, EpCAM-positive) were isolated from KPV+/+ and KPV−/− lungs at 6 w.p.i. with Ad-Cre (hereafter referred to as KPV+/+ and KPV−/− cells)." (PMID 37161053, 2023). "We detected cancer cells using markers typical of LUAD and alveolar epithelium (EPCAM, CDH1, KRT19, KRT18, KRT8)." (PMID 37745301, 2023). "The role of TFCP2L1 in driving expression of epithelial genes was reinforced by analyses of the Cancer Cell Line Encyclopaedia (CCLE) showing positive correlation between TFCP2L1 (and also OVOL2) and EPCAM." (PMID 37236926, 2023). "Consistently, the biomarkers of cancer stem cells - CD44 and EpCAM - were both downregulated in circRABL2B overexpressed cells." (PMID 37324942, 2023).
cancer (continued). "In their work, the authors analyzed the presence of other cancer stem cell markers, including CD44+/CD24+/EPCAM+ and CD133+." (PMID 37371030, 2023). "We also found that our EpCAM neutralizing antibody, EpAb2-6, attenuates the phosphorylation of HGFR and inhibits cancer cell metastasis." (PMID 37543570, 2023). "Among the ligands, this compound (1,2-benzenedicarboxylic acid) exhibited the highest binding affinity, particularly with crucial cancer-related genes, including MET, EPCAM, PTEN, and CHEK2." (PMID 38116103, 2023). "Dual-RevCAR T-cells secreted increased amounts of GM-CSF, IFN-γ, IL-2 and TNF-α only upon engaging CEA+ EpCAM+ cancer cells upon simultaneous presence of anti-CEA and anti-EpCAM RevTMs." (PMID 38169746, 2023). "It has been discovered that the ectopic overexpression of EpCAM and HER2 in cancer cells induces humoral immune responses in patients." (PMID 37375854, 2023). "To investigate the morphology of cancer cells on tissue-engineered bone after MET, we stained the cells with cancer-specific protein, EpCAM, and compared our results with cells grown on a 2D surface." (PMID 40226410, 2023). "Most notably, the Cell Search platform, the first and only CTC counting equipment for cancer prognosis approved by the FDA, was developed for the positive immunoselection of CTCs through anti-EpCAM antibody-coated immunomagnetic beads." (PMID 38001632, 2023). "The CellSearch system, based on EpCAM, is the only commercially available product approved by both the FDA (approved in 2004) and CFDA (approved in 2012) for CTCs detection in malignant tumors." (PMID 38057833, 2023). "Surviving cancer cells that managed to escape the cytotoxic effects of GEM or 5‐FU were investigated for the expression of four CSC markers: ALDH1A1, PON1, CD44, and EpCAM." (PMID 36400567, 2023). "Differential expression analyses comparing cancer areas of rHGP and dHGP revealed established CRC cell markers, such as FABP1, CEACAM5, CLDN3, EPCAM and S100A10 in the rHGP (Supplementary Spreadsheet 1)." (PMID 36691028, 2023). "For example, the use of EpCAM antibody catumaxomab for the treatment of non-small-cell lung cancer shows high efficacy in reducing the expression of MYC and killing cancer cells." (PMID 36966168, 2023). "The ISET filter device exploits physical features, such as size, that differentiate cancer cells from normal hematopoietic cells, showing better potential for CTC quantification and monitoring than EpCAM-based techniques." (PMID 36675033, 2023). "We used fluorescence activated cell sorting (FACS) to analyze the population of CSCs using CD44, EpCam, and CD133 sorting as triple markers of cancer stem-like cells." (PMID 37231419, 2023). "EPCAM, aka CD326, is an oncogenic signaling molecule, a novel therapeutic target and cancer stem cell marker." (PMID 36639722, 2023). "Four different epitopes, previously related to cancer stem cells, were analyzed: BCRP1, EpCam, CD133, and AC133." (PMID 38001682, 2023). "Dimensionality reduction and graph-based clustering analysis identified 3 cancer cell clusters (clusters 1-3) and 3 CAF clusters (clusters 4-6), marked by expression of EPCAM and Vimentin respectively." (PMID 37261365, 2023). "There are many molecular markers on the surface of CTC, and the most common is EpCAM, a common CTC marker for cancers of epithelial origin." (PMID 36911396, 2023). "The combination of EpCAM antibodies and chimeric CAR-T technology has been tested in phase I trials for various types of cancer, such as NCT02725125, NCT02915445, and NCT02729493." (PMID 36966168, 2023). "The detection of as few as 10 SKBR3 cancer cells isolated from a peripheral blood matrix (5 mL) was possible using the markers CK19, SCGB2A2, EpCAM, EMP2, MAL2 and PPIC." (PMID 36831613, 2023).
cancer (continued). "The markers most frequently used to identify cancer stem cells in solid tumors are CD44, CD133, CD24, epithelial cell adhesion molecule (EpCAM), interleukin 6 (IL-6) receptor, and leucine-rich repeat-containing G-protein coupled receptor 5 (LGR5)." (PMID 37237922, 2023). "The anti-cancer activity of prepared nanocarriers was evaluated on CD133, EpCAM and CD44 positive Caco-2 cells xenografted mice." (PMID 37149607, 2023). "An immunoblot analysis of EpCAM, E-cadherin (known epithelial cell markers), and vimentin (known mesenchymal cell markers) was performed to determine the effect of PYCR2 upon cancer cell phenotype." (PMID 37508547, 2023). "Relative cancer invasion markers matrix metalloproteinase 2 (MMP-2), E-cadherin, MMP-9, epithelial-cell adhesion molecule (EpCAM), and N-cadherin in the LOC model were detected via immunohistochemical (IHC) staining." (PMID 37771785, 2023). "The gene therapy using Ad-FZ33 with anti-EpCAM or anti-EGFR or anti-CEA antibodies is a potentially effective and safe therapeutic strategy for various cancers." (PMID 36678816, 2023). "After the modification of a specific anti-EpCAM antibody, MCF-7 cancer cells were captured successfully with a capture efficiency of 91%." (PMID 37109900, 2023). "EpCAM fulfills many functions in the regulation of cell adhesion, proliferation, migration, stemness, and epithelial-to-mesenchymal transition (EMT) of carcinoma cells." (PMID 36845124, 2023). "In pT2-4 carcinomas, the average TROP2 and EpCAM staining intensity was intermediate (61.8±40.9; 18.3±12.3)." (PMID 38282671, 2023). "Overall, we developed a targeted and pH-sensitive DDS based on EpCAM Apt-functionalized MSNs, which can successfully deliver 5-FU to CRC cells and enhance anti-cancer activity, while reducing systemic off-target toxicities." (PMID 36686226, 2022). "Membrane-bound EpCAM can be cleaved via regulated intramembrane proteolysis (RIP), which is frequently activated by cell–cell contact or soluble EpEX in cancers." (PMID 36369033, 2022). "To date, KRT19 remains the only keratin that has been reported to be one of the cancer stemness markers including CD133, EpCAM and c-kit in HCC." (PMID 35706019, 2022). "In connection to this, it seemspromising to combine different methods of affecting malignant tumors usingscaffold proteins that target both HER2 and EpCAM to develop effective cancertreatment strategies." (PMID 35441046, 2022). "The expression of EpCAM was found to be correlated with Ki67, CCND1 and phosphorylated Rb in many types of cancer." (PMID 36369033, 2022). "CD44 has been introduced as a cancer stem cells marker in HCC together with CD90, CD133, CD24, and EpCAM, and is reported to be involved in tumor initiation and growth, cancer progression, and promoting metastasis." (PMID 35164326, 2022). "Metformin has been shown to radiosensitize cancer cells and predominantly eradicate CSCs by the downregulation of genes, such as CD44 and EPCAM or by the inhibition of EMT." (PMID 35269569, 2022). "Markers of HCC stem cells, including CD44, EPCAM, and THYI (CD90), were expressed at the beginning of the cancer cell differentiation trajectory." (PMID 35967424, 2022). "EpCAM (epithelial cell adhesion molecule, CD326) is expressed on normal epithelial cells, but is highly over-expressed in many types of cancer." (PMID 35012489, 2022). "First, we used QPCR to detect several commonly used biomarkers of cancer stem cells, which are CD44, EpCAM, SOX2, C-MYC." (PMID 35816352, 2022).